PYDC5 (pyrin domain containing 5)
Description:
Functions as an inhibitor of DNA virus-induced activation of AIM2-like receptors (ALR) inflammasome through interaction with AIM2.
Synonyms: POP3
Tractability: No criterion of Open Targets' tractability assessment is met for any kind of drug.
Gene: Protein-coding gene on chromosome 1 (158,999,971 to 159,002,751, reverse strand). Ensembl gene ENSG00000289721.
Gene Ontology:
Molecular function: protein binding
Biological process: cellular response to interferon-beta; cellular response to virus; negative regulation of AIM2 inflammasome complex assembly; negative regulation of protein-containing complex assembly; cellular response to cytokine stimulus; regulation of innate immune response
Homologues: Orthologues: chimpanzee PYDC5 (96% identical).